DVL3 (dishevelled segment polarity protein 3)
Diseases named in the same sentence as DVL3 in open-access papers (continued):
Sharing a sentence is not in itself a finding about the gene and the disease.
aortic valve calcification (1 paper, 2024). "Taking into account the lower systolic and diastolic blood pressure in carriers of C allele of rs73185723 in the DVL3 gene, we can assume that the carriers of these variants are more prone to aortic valve calcification independently of other CAVD risk factors and of valve morphology." (PMID 39057646, 2024).
autosomal dominant Robinow syndrome (1 paper, 2025). Autosomal dominant Robinow syndrome (DRS) is the more common type of Robinow syndrome (RS) characterized by mild to moderate limb shortening and abnormalities of the head, face and external genitalia. "All variants known to cause autosomal dominant Robinow syndrome occur in genes within the Wnt signaling pathway (DVL1, DVL3, or WNT5A)." (PMID 40796658, 2025).
cervical tumor (1 paper, 2013). "IHC analysis showed that remarkable increased expressions of DVL3 and β-catenin were observed in cervical tumor sections as compared with the normal cervix sections." (PMID 23301094, 2013).
DiGeorge Syndrome (1 paper, 2019). "DVL1 has been reported to be a candidate gene for human development disorder Schwartz‐Jampel syndrome, Charcot‐Marie‐Tooth disease type 2A and DiGeorge Syndrome, while DVL3 have been linked to Hirschsprung's disease." (PMID 30468298, 2019).
endometrioid carcinoma (1 paper, 2018). "The Wnt pathway is activated either by β-catenin exon 3 mutations in low-grade endometrioid carcinoma or by overexpression of Dvl3 protein in high-grade endometrioid carcinoma." (PMID 29731976, 2018).
esophageal cancer (1 paper, 2019). A primary or metastatic malignant neoplasm involving the esophagus. "The results showed a significant correlation between the expression levels of SPINK5 and β‐catenin (CTNNB1), LRP5, LRP6, DVL3, LEF1, AXIN2, MYC, and cyclin D1 (CCND1) in esophageal cancer." (PMID 30868765, 2019).
leukemia (1 paper, 2016). A malignant (clonal) hematologic disorder, involving hematopoietic stem cells and characterized by the presence of primitive or atypical myeloid or lymphoid cells in the bone marrow and the blood. "Similarly in migrating leukemia cells, Dvl-3 (part of the Fzd complex) localizes to the leading edge while Vangl2 localizes to the trailing edge." (PMID 26990447, 2016).
mental disorder (1 paper, 2022). A disease that has its basis in the disruption of mental process. "Although research on DVL3 role in mental disorders has just started, it has been found that its mRNA expression levels is significantly decreased in the nucleus accumbens and frontal regions of those patients who are depressed." (PMID 35126809, 2022).
mesothelioma (1 paper, 2021). A usually malignant and aggressive neoplasm of the mesothelium which is often associated with exposure to asbestos. "We have revealed that suppressing disheveled‐3 (Dvl‐3) in the Wnt signaling pathway elicited antitumor effects in mesothelioma cell lines." (PMID 33319489, 2021). "Furthermore, we found that reduced protein expression of heat shock protein 70 (HSP70) was accompanied by Dvl‐3 suppression in mesothelioma cells by the use of two‐dimensional gel electrophoresis." (PMID 33319489, 2021).
microcephaly (1 paper, 2016). A congenital or acquired developmental disorder in which the circumference of the head is smaller than normal for the person's age and sex. "Through Drosophila and in-vitro experiments, we show that ALFY controls Wnt signaling by regulating DVL3 aggregation, likely in an autophagy-dependent manner, unveiling novel molecular pathways of normal brain development and primary microcephaly." (PMID 27008544, 2016). "Thus, Wnt signaling, controlled by ALFY-mediated aggregate removal of DVL3, determines human brain size and human microcephaly." (PMID 27008544, 2016).
mood disorder (1 paper, 2024). A cognitive disorder a disturbance in which the person's mood is hypothesized to be the main underlying feature. "The role of the DVL3 signaling pathway in mood disorders is well known." (PMID 37501340, 2024).
mucinous adenocarcinoma (1 paper, 2023). An invasive adenocarcinoma composed of malignant glandular cells which contain intracytoplasmic mucin. "The results indicated that the mRNA level of DVL3 was increased in CRC tissues including adenocarcinoma and mucinous adenocarcinoma, compared to normal tissues." (PMID 37147666, 2023).
myopia (1 paper, 2021). "The expression of Dvl3 was significantly increased in the retina with FD myopia than that in the lateral eyes and that in control animals (P < 0.05, 1-way ANOVA) after treatment for 7 and 28 days." (PMID 34259818, 2021). "In our study, we also found that orally administered niclosamide inhibited the canonical Wnt signaling pathway activation, downregulated Dvl3, decreased downstream β-catenin signaling, and exerted anti-extension of AL and VCD in the FD myopia mice and APCMin mice." (PMID 34259818, 2021).
nasal polyps (1 paper, 2023). "The expression levels of DVL1, DVL3 and FZD3 mRNAs were significantly lower in the nasal polyps than in the turbinates, while those of FZD6, PRICKLE1, PRICKLE2, VANGL1 and VANGL2 mRNAs were not statistically different between the two tissues." (PMID 38232516, 2023).
neuroblastoma (1 paper, 2016). Neuroblastoma (NB) is the most common solid, extracranial childhood tumor. "To test this hypothesis, we transiently co-transfected neuroblastoma (SH-SY5Y) cells with constructs harboring human DVL1, DVL2 or DVL3 with a FLAG epitope tag in the N-terminus and EGFP in the C-terminus." (PMID 27008544, 2016).
Parkinson disease (1 paper, 2019). A progressive degenerative disorder of the central nervous system characterized by loss of dopamine producing neurons in the substantia nigra and the presence of Lewy bodies in the substantia nigra and locus coeruleus. "When we compared the Z-scores obtained from these two TWAS, we found that 12 genes discovered in International Parkinson Disease Genomics Consortium (IPDGC) cohort (e.g., MAPT, SNCA, ATG14, DVL3, and MTOR) could be replicated." (PMID 30824768, 2019).
pneumonia (1 paper, 2012). An acute, acute and chronic, or chronic inflammation focally or diffusely affecting the lung parenchyma, caused by an infection in one or both of the lungs (by bacteria, viruses, fungi, or mycoplasma.). "There were two specimens with pneumonia and one specimen positive for tuberculosis that gave false-positive results by detecting DVL-3 mRNA, and four specimens with pneumonia and one specimen positive for tuberculosis that gave false-positive results by detecting δ-catenin mRNA, respectively." (PMID 22461838, 2012).
prostate tumors (1 paper, 2016). "Compared to the normal prostate tissues or primary prostate tumors, the mRNA levels of DVL3, MAPK9, and CTNNB1 are higher in metastatic prostate tumors while the mRNA level of ROR2 is lower in metastatic prostate tumors." (PMID 27191743, 2016). "Gene expression of FZD5, DVL3, RELA, MAPK9, CTNNB1, and SNAI1 is higher in metastatic prostate tumors as compared to primary prostate tumors." (PMID 27191743, 2016).
rapidly progressive glomerulonephritis (1 paper, 2021). Inflammation of the glomeruli that is characterized by a rapid loss in renal function with glomerular crescent formation observed on biopsy; it is often seen in patients with concomitant autoimmune disease, like Goodpasture's syndrome or systemic lupus erythematosus. "The NTN model mirrors human rapidly progressive glomerulonephritis (RPGN), and recently, transcripts for VANGL1, VANGL2, CELSR2, DVL2, DVL3, PK1, and PK2 were found to be significantly upregulated in two independents cohorts of RPGN biopsies compared to living kidney donor controls." (PMID 33716764, 2021).
rhabdomyosarcoma (1 paper, 2022). A rare aggressive malignant mesenchymal neoplasm arising from skeletal muscle. "DVL1 and DVL3 also contribute to regulation of proliferation in rhabdomyosarcoma." (PMID 35589804, 2022). "Considering the impact of manipulation of DVL1 or DVL3 on skeletal myoblast proliferation, we investigated the role of the DVL proteins in rhabdomyosarcoma." (PMID 35589804, 2022).
sarcoma (1 paper, 2005). A usually aggressive malignant neoplasm of the soft tissue or bone. "The antibody induced cell death in these sarcomas and decreased levels of Dvl-3 and β-catenin in A-204 and SJSA-1 cell lines." (PMID 15913453, 2005).
Umbilical hernia (1 paper, 2021). Protrusion of abdominal contents through a defect in the abdominal wall musculature around the umbilicus. "Vertebral segmentation defects and ribs fusion occur in the recessive form linked to ROR2 mutations (MIM# 268310) whereas umbilical hernia and supernumerary teeth are more common in the autosomal dominant forms due to WNT5A (MIM# 180700), DVL1 (MIM# 616331), DVL3 (MIM# 616894) mutations." (PMID 35096710, 2021).
cancer (30 papers, 2009 to 2025). A tumor composed of atypical neoplastic, often pleomorphic cells that invade other tissues. "Actually, DVL3 has been implicated in multiple malignant behaviors, including cell proliferation, metastasis and cancer stem cell properties." (PMID 36460966, 2022). "As Dvl is an important mediator of the Wnt signaling pathway which is implicated in cancer stem cell maintenance in other cancers, we examined the role of Dvl3 in regulating the stemness features in HCC." (PMID 28455968, 2017). "Meanwhile, the level of DVL3 protein in cancer cells (HT-29, HCT-8, SW480, SW620, HCT116) was higher than that in normal CRC epithelial cells." (PMID 40308773, 2025). "DVL1 is associated with poor prognosis, DVL2 promotes tumor proliferation and invasion through interaction with PWP1, and DVL3 drives cancer cell invasion and metastasis via Wnt5B-regulated signaling." (PMID 39594618, 2024). "We observed an upregulation of CTNNB1 and other genes involved in CTNNB1 stabilization (CSNK2A1, CSNK2B, DVL2, DVL3,) in rHGP cancer areas." (PMID 36691028, 2023). "As a member of the disheveled segment polarity proteins that act as signal amplifiers in the Wnt pathway, DVL3 significantly promotes the development of malignant tumors." (PMID 36614043, 2022). "In contrast to WWOX and DVL2, expression rates of DVL1 and DVL3 were higher in cancer cell lines compared to normal 26-28." (PMID 32368285, 2020). "Consistently, DVL3 is most abundant in the human cancer cell lines panel, indicating that DVL3 is mainly expressed in human cancer." (PMID 29895829, 2018). "We have shown that Dvl3 promoted cancer stemness in terms of enhanced tumorigenicity, sphere formation ability, chemoresistance, and expression of stemness genes." (PMID 28455968, 2017). "Supervised hierarchical analysis using ANOVA further revealed differential expression of several proteins implicated in cancer, including BRAF, STAT5A, and the Wnt pathway-related protein DVL3." (PMID 25999352, 2015). "The understanding of the regulation of AMPK activators on DVL3 will assist in the exploration of alternative anti-cancer drugs for clinical usage." (PMID 23301094, 2013). "Examples include members of the MAPK signaling pathway, such as NRAS, a known oncogene; and members of the WNT signaling pathway, DVL2, DVL3, APC and TCF7 which have been previously implicated in colorectal and other cancers." (PMID 19997598, 2009). "Finally, the canonical Wnt signaling pathway, which shapes the stem cells-like properties of cancer cells and boosts proliferation, was downregulated at the level of a protein Dishevelled (DVL3) and GSK3 beta kinase (GSK3B)." (PMID 39495207, 2024). "The DVL3 regulatory axis may be disrupted in future ESCC treatments to reduce the spread of cancer and enhance patient outcomes as research continues to provide insight into the complexity of this signaling system." (PMID 39594618, 2024). "Disheveled3 (DVL3) is involved in malignant behaviors of cancer." (PMID 37147666, 2023). "Additional experiments indicated that IND-2 could produce its anti-cancer efficacy by inducing oxidative stress, decreasing the mitochondrial membrane potential and inhibiting metastasis by altering the levels of Wnt 5a/b, DVL3, E-cadherin and cyclin B1." (PMID 36431014, 2022). "During tumor development, myriad oncogenic pathways such as DVL3/Wnt/β-catenin, AKT/ERK/FOXM1, and mTOR/p70S6K signals etc. are constitutively activated in cancer cells." (PMID 35743298, 2022). "This post-translational modification of Dvl3 in turn maintains LGR5 expression and enhances the cancer stemness properties in HCC." (PMID 28455968, 2017). "Targeting circ_0000277 could decrease DVL3 levels, therefore resulting in the suppression of the aggressive behaviors of ESCC cells and offering a novel approach to treating this cancer." (PMID 39594618, 2024).
cancer (continued). "We proposed a mechanism in which the up-regulation of DVL3 eventually activated the target gene NRCAM, which may promote cancer cell proliferation and metastasis." (PMID 39252305, 2024). "Moreover, DVL3 regulates IGF receptor-1 (IGF-IR), a promising new therapeutic target in several cancers, by mediating the IGF-RAS signaling pathway." (PMID 37859822, 2023). "Not only do DVLs bind to multiple tissue-specific aromatase promoters that are aberrantly activated in cancer, but the role of DVL-1 vs. DVL-3 appears to play a promoter-specific and cell- type dependent role that can lead to either activation or repression of CYP19A1 transcripts." (PMID 30479694, 2018). "Importantly, cancer spheroids isolated from group B ascites, i.e. non-activating WNT signaling, showed limited phosphorylation of DVL2 and DVL3 that was not further reduced by LGK974 treatment." (PMID 31903136, 2020).
tumor (27 papers, 2009 to 2024). "Stronger DVL1 expression was associated to low‐grade tumours and strong DVL3 expression to high‐grade tumours." (PMID 30468298, 2019). "Given their association with poor prognosis, targeting DVL2 and DVL3 in HCC could offer new therapeutic strategies to inhibit tumor progression and improve patient outcomes." (PMID 39594618, 2024). "Our study explored DVL1, DVL2 and DVL3 gene alterations in association with tumour grade." (PMID 30468298, 2019). "Statistical analysis pointed out that deletions of DVL3 gene were significantly associated to the highest grade (P = 0.007) and could be connected to tumour progression." (PMID 30468298, 2019). "LOHs of DVL3 gene were significantly associated with grade IV tumours (P = 0.007)." (PMID 30468298, 2019). "The elevated expression of DVL proteins, particularly DVL2 and DVL3, suggests their major involvement in the development of the tumor." (PMID 39594618, 2024). "Similar results were also found for ANKS6; on the other hand, the expression of DVL3 was positively related with tumor’s histological grade, being the highest in grade 4 and the lowest in grade 1 ccRCC." (PMID 39596188, 2024). "The results showed that DVL3 promoted the proliferation and migration of ESCC cells, whereas silencing DVL3 significantly inhibited these tumor properties and suppressed tumor formation by promoting apoptosis." (PMID 39594618, 2024). "The protein expression level of DVL3 was verified by immunoblotting, and the results indicated that DVL3 was overexpressed in tumor tissues compared with normal tissues." (PMID 37859822, 2023). "Expression rates of DVL1 and DVL3 were higher in the SCC-15 tumor cell line compared to the HET-1A normal cell line." (PMID 32368285, 2020). "While, Dvl-1 protein levels were increased in the nuclei of the tumor tissues, there was a decrease in the nuclear levels of the Dvl-2 and Dvl-3 proteins." (PMID 32368285, 2020). "With regard to subcellular localization of DVL3 we noticed that tumours with low signal intensities showed predominant cytoplasmic localization, while moderate and strong expression was usually localized in both the cytoplasm and the nucleus (P = 0.004)." (PMID 30468298, 2019). "Lower tumour grades (I and II) showed significantly higher levels of DVL1 expression than high grades (III and IV), while strong DVL3 expression was significantly associated to high‐grade tumours." (PMID 30468298, 2019). "Dvl3 knockdown in Huh-7 cells reduced the incidence of tumor formation in vivo as compared to the NTC group." (PMID 28455968, 2017). "A similar trend was observed in Dvl3-knockdown MHCC-97L cells, and there was a reduction in the incidence of tumor formation with injection of 5 × 104 Dvl3-knockdown cells as well as a delay in tumor onset." (PMID 28455968, 2017). "In this study, we found that, in human HCCs, Dvl3 was overexpressed at protein level as compared with the corresponding non-tumor livers." (PMID 28455968, 2017). "Tumor volume was inhibited by silencing DVL3 in vivo compared to the control." (PMID 37147666, 2023). "Importantly, overexpression of DVL3 was inactive in terms of YAP nuclear export in A549 cells, indicating that loss of LKB1 tumor suppressor abolishes DVL’s YAP nuclear export function." (PMID 29895829, 2018). "Additionally, we identified that DVL3 was also a potential tumor-promoting gene in EC." (PMID 36614043, 2022). "However, the roles of individual Dvls and whether DVL3 overexpression is related to tumor prognosis are still poorly defined." (PMID 29200599, 2017). "The expressions of miR-4516 were lower, while the expressions of Wnt 8B, DVL3, FOSL1, CDK1, CDK2, CCNA1, and CCNB1 were enhanced in tumor tissue compared to normal lung tissue in the human samples." (PMID 38930863, 2024).